DUX4L9 (double homeobox 4 like 9 (pseudogene))
Description:
Down-regulates MYOD1 expression and may up-regulate MYF5 expression. May regulate microRNA (miRNA) transcription, up-regulating the expression of some myogenic miRNAs, including MIR1-1, MIR133A2, MIR133B and MIR206. Impairs the differentiation of myoblasts and may be involved in muscle regeneration. Reduces DUX4-induced nuclear localization of CTNNB1/beta-catenin and its subsequent activation of target genes.
Synonyms: DUX4c
Gene: Unprocessed pseudogene on chromosome 4 (190,021,407 to 190,022,665, reverse strand). Ensembl gene ENSG00000224807.
Subcellular location: Nucleus; Cytoplasm
Diseases named in the same sentence as DUX4L9 in open-access papers:
DUX4L9 is named in the same sentence as 7 diseases in open-access papers, as found by Europe PMC text mining. Sharing a sentence is not in itself a finding about the gene and the disease.
DUX4L9 shares sentences with these, for which no sentence is quoted: facioscapulohumeral muscular dystrophy (4 papers); Duchenne muscular dystrophy (3); rhabdomyosarcoma (3); breast tumor (1); cancer (1); desminopathies (1); retinopathy (1).